RNU6-209P (RNA, U6 small nuclear 209, pseudogene)
Gene: Small nuclear RNA gene on chromosome 5 (164,935,162 to 164,935,268, reverse strand). Ensembl gene ENSG00000206845.
Homologues: Orthologues: chimpanzee U6 (97% identical), guinea pig U6 (89% identical), macaque U6 (88% identical), dog U6 (86% identical), dog U6 (83% identical), guinea pig U6 (75% identical). Paralogues in human: RNU6-26P (91% identical), RNU6-949P (91% identical), RNU6-1011P (90% identical), RNU6-1145P (90% identical), RNU6-12P (90% identical), RNU6-13P (90% identical), RNU6-166P (90% identical), RNU6-25P (90% identical), RNU6-31P (90% identical), RNU6-32P (90% identical), RNU6-35P (90% identical), RNU6-38P (90% identical), and 1288 more.